RNF175 (ring finger protein 175)
Synonyms: FLJ34190
Tractability: Antibody: UniProt predicts a signal peptide or a membrane-spanning region.
Gene: Protein-coding gene on chromosome 4 (153,710,160 to 153,760,031, reverse strand). Ensembl gene ENSG00000145428.
Subcellular location: Membrane
Gene Ontology:
Molecular function: protein binding; ubiquitin protein ligase activity; metal ion binding
Biological process: ERAD pathway
Cellular component: endoplasmic reticulum membrane; Golgi membrane; membrane
Genetic constraint (gnomAD): Loss-of-function variants: 19 observed, 28.21 expected, observed/expected ratio (o/e) 0.67, 90% interval 0.47 to 0.99. The upper end of that interval is the gene's LOEUF score, 0.99, which puts it in group 4 of 6, group 1 being the genes least tolerant of losing a copy. Missense variants: 260 observed, 280.92 expected, observed/expected ratio (o/e) 0.93, 90% interval 0.84 to 1.03. Synonymous variants: 118 observed, 99.09 expected, observed/expected ratio (o/e) 1.19, 90% interval 1.02 to 1.39.
Homologues: Orthologues: chimpanzee RNF175 (99% identical), macaque RNF175 (97% identical), rabbit RNF175 (92% identical), dog RNF175 (86% identical), zebrafish rnf175 (73% identical), Drosophila melanogaster CG15814 (54% identical), Caenorhabditis elegans rnf-121 (46% identical). Paralogues in human: RNF121 (68% identical).
Diseases named in the same sentence as RNF175 in open-access papers:
RNF175 is named in the same sentence as 3 diseases in open-access papers, as found by Europe PMC text mining. Sharing a sentence is not in itself a finding about the gene and the disease. The quoted sentences say what the papers report.
breast carcinoma (1 paper, 2022). "Analysis of rare missense variants identified evidence of associations of TMEM161A, SIPA1L1, and ERCC2 with overall breast cancer, RNF175 and NCKAP1L with ER-positive disease, and SLC22A10, PHAX, SMARCA2, EML5, NTRK3, and MED23 with ER-negative disease." (PMID 35884425, 2022). "When missense variants were assessed, three further associations were observed for overall breast cancer (TMEM161A, SIPA1L1, ERCC2), and a further seven were observed for subtypes (RNF175, NCKAP1L, PHAX, SMARCA2, EML5, NTRK3, MED23)." (PMID 35884425, 2022). "The best putative candidates in this group were TMEM161A, ERCC2, and SIPA1L1 for overall breast cancer, RNF175 and NCKAP1L for ER-positive disease, and PHAX, SMARCA2, NTRK3, EML5, and MED23 for ER-negative disease." (PMID 35884425, 2022).
RNF175 also shares sentences with these, for which no sentence is quoted: inflammatory bowel disease (1 paper); Sepsis (1).